PIN1 (peptidylprolyl cis/trans isomerase, NIMA-interacting 1)
Diseases named in the same sentence as PIN1 in open-access papers (continued):
Sharing a sentence is not in itself a finding about the gene and the disease.
breast carcinoma (continued). "In addition, our study demonstrates the regulatory role of PIN1 in breast cancer tumorigenesis induced by IL-34." (PMID 33800170, 2021). "Furthermore, GRK2-HDAC6-mediated deacetylation of the lysine 46 residue on Pin1 enhances Pin1 stability and promotes higher substrate affinity and isomerase activity in breast cancer cells." (PMID 33807199, 2021). "Interestingly, NOTCH1 signaling upregulates Pin1 expression, thereby generating a positive feedback loop for malignant progression in human breast cancers." (PMID 33807199, 2021). "In addition, Pin1 enhances tamoxifen resistance through upregulation of LC-3, leading to the induction of protective autophagy in breast cancer cells." (PMID 33807199, 2021). "Furthermore, treatment with KPT-6566 inhibited the overexpression of Pin1, confirming the reduction of breast cancer stem cells." (PMID 32258027, 2020). "Moreover, Pin1 has been shown to increase self-renewal activity and promote breast cancer stem cell-mediated tumorigenesis." (PMID 32195254, 2020). "Similarly to Pin1, CyPA is found overexpressed in different types of tumours, including breast cancer, and in some reports a correlation between CyPA overexpression and malignant transformation has been reported." (PMID 33037285, 2020). "Furthermore, Pin1 can directly regulate the adjacent DNA binding domain of ERα in an allosteric manner, enhancing the DNA binding function of ERα to drive breast cancer proliferation." (PMID 32296699, 2020). "PIN1 regulates the tumorigenesis and expansion of CSCs in leukemia and breast cancer." (PMID 32258027, 2020). "In addition, Juglone and ATRA have been shown to potently reduce PIN1’s oncogenic activity in breast cancer models; however, the efficacy of these drugs on reducing MYC’s oncogenic activity remains to be studied." (PMID 32300594, 2020). "Pin1 increases the tamoxifen resistance upregulating LC-3 in breast cancer." (PMID 32258027, 2020). "Overexpression of Pin1 in cancer cells and tissues has been proved to be correlated with enhanced NF‐κB activation and malignant biological properties in human hepatocellular carcinoma, glioblastoma and breast cancer." (PMID 32347623, 2020). "It has been reported that the immunophilin Pin1 is overexpressed in breast cancer and that its up-regulation is prevalent in ERBB2-positive tumours; however, its silencing or functional inhibition does not potentiate TZ activity, possibly because it accelerates receptor degradation." (PMID 33037285, 2020). "Furthermore, Pin1 pSer16 levels have been shown to be positively correlated with COT levels in human breast cancer." (PMID 32195254, 2020). "Studies have shown a role of PIN1 in stem cells of breast cancer and leukemia." (PMID 32258027, 2020). "In human breast cancer, PIN1 promotes oncogenesis via the cyclin D1 regulation." (PMID 32258027, 2020). "RUNX3, a tumor suppressor in breast cancer, has been identified as a Pin1 substrate." (PMID 32266261, 2020). "In addition, the suppression of Pin1 leads to the sensitization of breast cancer cells to different drugs." (PMID 32010480, 2020). "Binding of Pin1 and the subsequent Pin1-mediated conformational change via isomerization increases ERα DNA binding activity with a concomitant increase in ERα transcriptional activity in estrogen activated breast cancer cells." (PMID 32266261, 2020). "Pin1 transgenic mice in mammary glands induces mammary hyperplasia and malignant mammary tumors." (PMID 32258027, 2020). "Moreover, in breast cancer cells with high levels of PIN1, NOTCH1 signaling is strongly activated despite presence of FBXW7, inciting expansion of breast cancer stem cells (CSC) and tumorigenesis." (PMID 30873382, 2019). "These two cell lines expressed very low level of Pin1, comparing to breast cancer cell lines." (PMID 31867329, 2019).
breast carcinoma (continued). "Fifth, PIN1 knockdown or pharmacological inhibition sensitizes cancer cells of different origins to chemo- and target therapy, such as breast cancers to 5-fluorouracil, Taxol, and rapamycin, hepatocellular carcinoma to sorafenib, colon cancer to Taxol and acute myeloid leukemia to retinoic acid." (PMID 30873382, 2019). "However, few studies assess the potential of Pin1 inhibitor in treating TAMR breast cancer in vitro and in vivo." (PMID 31867329, 2019). "Here we found that Pin1 was up-regulated in tamoxifen-resistant breast cancer cells." (PMID 31867329, 2019). "Thus, ATRA induced the degradation of Pin1 and suppressed cell viability and proliferation of tamoxifen-resistant breast cancer cells." (PMID 31867329, 2019). "As a result of enhancing cellular uptake of ATO, combined treatment of ATO with ATRA synergistically reduces PIN1 expression, suppresses multiple PIN1-regulated oncogenic pathways, and inhibits breast cancer cell proliferation in vitro and in vivo as compared with ATO or ATRA alone." (PMID 32010690, 2019). "Knockdown of Pin1 by siRNA inhibits the viability of TAMR breast cancer cells, indicating that Pin1 might be a promising therapeutic target for tamoxifen-resistant breast cancer." (PMID 31867329, 2019). "In addition, pharmacological inhibition of PIN1 dampens mammary tumor growth in a Myc/NeuNT mouse model and metastasis development in a breast cancer xenograft." (PMID 30873382, 2019). "Therefore, targeting Pin1 by ATRA promised a new potential approach to treat tamoxifen-resistant breast cancer." (PMID 31867329, 2019). "Therefore, Pin1 overexpression promotes the growth of tamoxifen-resistant breast cancer cells by up-regulating the ligand-independent ERα activity." (PMID 31867329, 2019). "Pin1 has been found to be up-regulated in tamoxifen-resistant breast cancer." (PMID 31867329, 2019). "The purpose of our study was to reveal how PTOV1 and PIN1 coordinate to drive breast cancer progression, towards this end we used siRNA silencing approach to find out the change in expression profile of various oncogenic signal molecules at transcription and translation levels in MDA-MB-231 cells." (PMID 31083670, 2019). "In conclusion, ATRA-induced Pin1 ablation inhibits tamoxifen-resistant breast cancer growth by suppressing multifactorial mechanisms of tamoxifen resistance simultaneously, which demonstrates an attractive strategy for treating aggressive and endocrine-resistant tumors." (PMID 31867329, 2019). "Similarly, MAP3K-related serine-threonine kinase can phosphorylate serine 16 of PIN1, leading to increased cyclin D1 abundance and enhanced tumorigenesis in breast cancer cells." (PMID 30314361, 2018). "Conversely, PIN1-null mice are resistant to breast cancer induced by overexpression of oncogenes." (PMID 30314361, 2018). "We next assessed whether the PIN1-LYN regulatory mechanism is likely to be more widely applicable than just to BRCA1 breast cancer." (PMID 30590041, 2018). "Thus, ATO’s ability to inhibit breast cancer is positively correlated with Pin1 degradation and AQP9 expression." (PMID 30093655, 2018). "Besides the well-known role of Pin1 in tumorigenesis, recent studies have revealed that Pin1 dysregulation plays an important role in cancer stem cells (CSCs) in breast cancer and leukemia." (PMID 29848341, 2018). "However, in Huh-7 HCC cells, Pin1 was only degraded efficiently at 50 μM, a much higher dose in comparison with the breast cancer and APL cells." (PMID 28262728, 2017). "Interestingly, one of the critical protein in balancing Tau turnover is Pin1, a direct target of Notch1 in breast cancer cells." (PMID 27364742, 2016). "Furthermore, Pin1 overexpression significantly correlates with Rb hyperphosphorylation in human breast cancer biopsy samples." (PMID 25675300, 2015). "Moreover, the overexpression of Pin1 is correlated with Rb hyperphosphorylation in breast cancer biopsies." (PMID 25675300, 2015).
breast carcinoma (continued). "This likely occurs in breast cancer, where NOTCH1 or FBXW7 manifest low mutational rates and where, instead, high levels of Pin1 are frequent and strongly correlate with activated N1-ICD." (PMID 24357640, 2014). "Notably, the average expression value of NDT gene signature was contingent on PIN1 mRNA levels, while FBXW7 was non influential, therefore highlighting the biological dominance of Pin1 over Fbxw7α in regulating Notch signaling in breast cancer." (PMID 24357640, 2014). "From a clinical perspective, Pin1 promises to be a critical target in aggressive breast cancers." (PMID 24357640, 2014). "Clinical implications of our findings are relevant for breast cancer, since inhibition of Pin1 could suppress aggressive phenotypes through CSC exhaustion as well as recovered sensitivity to chemotherapeutic drugs." (PMID 24357640, 2014). "Strikingly, all the samples simultaneously displaying high N1-ICD and high FBXW7 expression, also expressed high levels of PIN1, indicating that in a consistent proportion of breast cancer patients (11/43 cases) high N1-ICD levels coexist with Fbxw7α thanks to high Pin1 expression." (PMID 24357640, 2014). "Also in the SK-BR-3 breast cancer cell line the half-life of overexpressed N1-ICD was strongly reduced from 2 h to 40 min upon Pin1 siRNA treatment with respect to control silencing." (PMID 24357640, 2014). "Moreover we found that also in vivo, in breast cancer tissues, the expression of Pin1 colocalized with Aldh-positive cells." (PMID 24357640, 2014). "We used Pin1 siRNA inhibition to down-regulate Pin1 in Her2-positive breast cancer cells." (PMID 19077306, 2008). "Pin1 -/- mice are largely protected from breast cancers induced by the c-neu transgene." (PMID 19077306, 2008). "In breast cancer, Pin1 levels are increased more in high grade than in low grade tumors." (PMID 19077306, 2008). "The sensitization of Her+ breast cancer cells to Rapamycin by Pin-inhibition was expected as Pin1 regulates signaling both up- and downstream from mTOR, thereby likely rendering these cells more vulnerable to growth arrest as a consequence of Pin1 inhibition." (PMID 19077306, 2008). "While 100% of the MMTV-Ras and over 90% of the MMTV-Neu transgenic mice in the wild-type Pin1 background developed one or several breast cancers within 75 weeks of observation, over 85% of transgenic mice in the Pin1 -/- background remained breast cancer-free over the same period." (PMID 19077306, 2008). "We therefore hypothesized that inhibition of Pin1 might block the growth of Her2-positive breast cancer cells." (PMID 19077306, 2008). "The overexpression of Pin1 in a majority of Her2-overexpressing breast cancer may contribute to maintain erbB2 levels." (PMID 19077306, 2008). "122/223 (54%) were Pin1 + (3+ index), 40/64 (62.5%) of Her2+ breast cancer were also Pin1+." (PMID 19077306, 2008). "For breast cancer, the PIN1/METTL3 axis may offer an alternative therapeutic target." (PMID 40919129, 2025). "Consistently, in the CPTAC human breast cancer dataset, the protein levels of Geminin, a well-characterized APC/CCDH1 substrate, were positively correlated with PIN1 protein abundance, whereas low levels of APC/CCDH1 were associated with poor prognosis of BC." (PMID 38622115, 2024). "Moreover, the expression of PIN1 also negatively correlated with pVHL in ER+ breast cancer samples." (PMID 36813923, 2023).
breast carcinoma (continued). "For instance, a Pin1 inhibitor all-trans retinoic acid has been used to treat acute promyelocytic leukemia in animal models and human patients, and all-trans retinoic acid reduced the growth of transplanted tamoxifen-resistant human breast cancer cells in mice." (PMID 36829834, 2023). "Therefore, Pin1 is considered an important target for designing novel anti-breast cancer drugs." (PMID 36014485, 2022). "Additionally, all-trans-retinoic acid, used for the treatment of acute promyelocytic leukemia treatment, suppressed breast cancer growth probably by inhibition of PIN1, being potentially an applicable approach for Notch inhibition when it is positively regulated by PIN1." (PMID 34680255, 2021). "Notably, PIN1 appears to act downstream of miR200c, so that miR200c may suppress the breast cancer stemness-promoting activity of PIN1, while PIN1 overexpression may overcome the inhibitory effect of miR200c." (PMID 32268506, 2020). "Thus, based on our findings, we determined whether pharmacological inhibition of PIN1 is sufficient to disrupt the FA pathway via FAAP20 destabilization in breast cancer, where high levels of PIN1 have been correlated with aggressiveness and chemoresistance." (PMID 30789902, 2019). "Indeed, we found that PIN1 inhibition in breast cancer xenografted mice sensitized tumors cells to paclitaxel treatment, not only by reducing the tumor mass but also by preventing the enrichment of the CSC population, a mechanism known to spur tumor recurrence after therapy." (PMID 30873382, 2019). "Moreover, in vitro studies have shown the ability of Pin1 to foster oncogenic mechanisms and in vivo models of breast cancer support the notion that Pin1 overexpression may favor tumor development." (PMID 28426725, 2017). "Pin1 binds to any of the four phosphorylated Ser/Thr-Pro sites on RUNX3 and downregulates its transcriptional activity and stability, thereby promoting breast cancer progression." (PMID 38727267, 2024). "For example, when Pin1 is inhibited, hepatocellular carcinoma (HCC) cells have been shown to become sensitive to sorafenib, breast cancer cells to trastuzumab and rapamycin, and colon cancer cells to taxol." (PMID 37375103, 2023). "Compounds 5, 8, and 12, which possess the highest anti-breast cancer activity against the MCF-7 cell line, were selected for Pin1 inhibition assay using tannic acid as a reference drug control." (PMID 36014485, 2022). "The data showed that compared with normal breast cancer, the expression levels of Pin1 and TAZ are increased in advanced breast cancer and are most significant in stage 4." (PMID 35450041, 2022). "Collectively, these results demonstrate that PIN1 regulates IL-36γ-induced MEK/ERK and JNK/c-Jun signaling pathways in breast cancer." (PMID 35954317, 2022). "This study observed a significant inverse correlation between Pin1 and CDK10 expression in tamoxifen-resistant breast cancer." (PMID 34277407, 2021). "PIN1 induces the ERE-binding affinity and transcription activity, and reduces the ERα degradation mediated by E3 ligase E6AP in breast cancer." (PMID 32258027, 2020). "A cyclic peptide derivative with increased cell permeable ability repressed the activity of PIN1 (IC50 = 32 nM) and inhibited the BT-474 breast cancer cell proliferation." (PMID 32258027, 2020). "Pin1 isomerizes the Ser118-Pro bond of ERα AF1 region to increase AF1 transcriptional activity, promoting the growth of tamoxifen-resistant breast cancer cells." (PMID 32296699, 2020).
breast carcinoma (continued). "Pin1 binds and targets PML for degradation in an ERK-dependent manner by targeting Ser403 and Ser505 of PML, inducing the development of breast cancer cells." (PMID 32296699, 2020). "Consistent with a relevant pathological role for GRK2-medited changes in Pin1 acetylation status, GRK2 expression and Pin1 levels and de-acetylation status correlate in both cell models and in samples from breast cancer patients." (PMID 31432234, 2019). "(ii) IRAK1 and PIN1 enzymatic activities are required for R-RT in cancer cell lines derived from multiple tumor types including HNSCC, breast cancer, colorectal cancer, and glioblastoma." (PMID 31799178, 2019). "Together, we have identified Pin1 as a novel positive regulator of YAP/TAZ in tumorigenesis and drug resistance of breast cancer cells." (PMID 31015482, 2019). "All together these results suggest that Pin1 positively regulates YAP/TAZ and work together to induce the Taxol resistance and tumorigenesis of breast cancer." (PMID 31015482, 2019). "PIN1 is also negatively controlled by tumor-suppressor microRNAs, such as miR-200b, a promoter of anoikis, miR-200c that restrains EMT in breast cancer, and by miR-296-5p in prostate cancer, and some others only recently identified." (PMID 30873382, 2019). "Here, we have shown that PIN1 and PTOV1 knockdown arrests breast cancer cell MDA-MB-231 in the G2/M phase of the cell cycle before entry into the mitosis where rapid synthesis of proteins is required for cell division." (PMID 31083670, 2019). "Moreover, previous data suggest that besides affecting ERα, Pin1 may promote tamoxifen resistance of breast cancer by activating growth-promoting pathways, down-regulating SMRT and cyclin dependent kinase, facilitating tumor angiogenesis and epithelial–mesenchymal transition." (PMID 31867329, 2019). "Our data showed that ATRA promoted the degradation of both Pin1 and ERα in TAMR breast cancer cells in a dose dependent manner." (PMID 31867329, 2019). "Accordingly, PIN1 and c-MYC were found co-over-expressed in breast cancer, driving a gene expression pattern largely composed of genes involved in ribosome biogenesis/ translation and metabolism and enriched in poor-outcome breast cancer subtypes." (PMID 30873382, 2019). "ATRA, a currently used target drug for acute promyelocytic leukemia (APL), mechanically combines with the substrate-binding site of Pin1 to inhibit its activation in APL and breast cancer cells." (PMID 30158600, 2018). "To further support ATO’s potent anticancer activity via targeting Pin1, we examined the effects of ATO on cell growth using 10 different human breast cancer cell lines." (PMID 30093655, 2018). "To demonstrate a direct functional link between PIN1 expression and LYN activity, we knocked down PIN1 in primary mouse Brca1 null cells and cells from a BRCA1 mutant human breast cancer cell line and the BRCA1 mutant PDX." (PMID 30590041, 2018). "In BRCA1-dysfunctional breast cancers, LYN activity is upregulated by a prolyl isomerase (PIN1) that is normally repressed by BRCA1." (PMID 30590041, 2018). "ATRA has been reported to inhibit and degrade active Pin1, resulting in the blockade of multiple Pin1-regulated oncogenic pathways in APL, breast cancer, and liver cancer." (PMID 29848341, 2018). "ATRA induced Pin1 protein degradation in HCC cells, although at a higher IC50 as compared with breast cancer cells, possibly due to a high ATRA metabolic enzyme in liver cells." (PMID 28262728, 2017). "Our data suggest that Pin1 acts as a key mediator for the effects of CYP3A4-derived 11,12-EET biosynthesis in TAM-resistant breast cancer." (PMID 29050342, 2017).